RN7SKP114 (RN7SK pseudogene 114)
Gene: Miscellaneous RNA gene on chromosome 9 (34,049,966 to 34,050,244, forward strand). Ensembl gene ENSG00000222259.
Homologues: Orthologues: chimpanzee 7SK (99% identical), guinea pig 7SK (73% identical), guinea pig 7SK (72% identical), guinea pig 7SK (71% identical), guinea pig 7SK (70% identical), guinea pig 7SK (68% identical), mouse Gm55487 (67% identical), guinea pig 7SK (66% identical), guinea pig 7SK (65% identical), guinea pig 7SK (62% identical), guinea pig 7SK (61% identical), guinea pig 7SK (60% identical), and 4 more. Paralogues in human: 7SK (74% identical), RN7SKP203 (74% identical), RN7SKP243 (74% identical), RN7SKP176 (73% identical), RN7SKP9 (73% identical), RN7SKP78 (72% identical), RN7SKP79 (72% identical), RN7SKP224 (72% identical), RN7SKP71 (72% identical), RN7SKP133 (72% identical), RN7SKP25 (72% identical), RN7SKP255 (72% identical), and 284 more.